ATG3 (autophagy related 3)
Diseases named in the same sentence as ATG3 in open-access papers (continued):
Sharing a sentence is not in itself a finding about the gene and the disease.
lymphopenia (1 paper, 2017). Reduction in the number of lymphocytes. "The lymphopenia upon specific deletion of Atg3, Atg5, Atg7, Atg16l1, or Vps34 in T cells has been demonstrated to be associated with increased percentages of activation/memory-like T cells within both the CD4+ and CD8+ compartments." (PMID 28572806, 2017). "Enhanced T cell activation/memory in the absence of Atg3, Atg5, Atg7, Atg16l1, or Vps34 can be partially attributed to peripheral T cell lymphopenia." (PMID 28572806, 2017).
malnutrition (1 paper, 2021). Inadequate nutrition resulting from poor diet, malabsorption, or abnormal nutrient distribution. "ATG3, ATG5, ATG7, or ATG16L1 deficiency in mice leads to malnutrition and energy expenditure, leading to death shortly after birth." (PMID 33854691, 2021).
myocardial ischemia (1 paper, 2020). A disorder of cardiac function caused by insufficient blood flow to the muscle tissue of the heart. "Among the dysregulated lncRNAs, RMRP was recently found to be upregulated by hypoxia in cardiomyocytes, and to aggravate myocardial ischemia-reperfusion injury by sponging miR-206 to target ATG3 expression." (PMID 31927529, 2020).
neuroblastoma (1 paper, 2016). Neuroblastoma (NB) is the most common solid, extracranial childhood tumor. "The expression of LC3B and ATG3, ATG5, ATG7, ATG12 proteins was also markedly up-regulated after BIX01294 treatment in neuroblastoma cells." (PMID 27934912, 2016).
nonalcoholic fatty liver disease (1 paper, 2025). "ATG3, essential for LC3 lipidation, is upregulated in patients and mice with nonalcoholic fatty liver disease (NAFLD) and promotes lipid accumulation." (PMID 40565288, 2025).
oral cancer (1 paper, 2022). "Moreover, increased expressions of Beclin-1, Atg3, Atg5, Atg7, Atg12, Atg 16, LC3-I, and LC3-II proteins indicated that 4-carbomethoxyl-10-epigyrosanoldie E triggered autophagy in oral cancer cells." (PMID 36275891, 2022).
primary effusion lymphoma (1 paper, 2023). A large B-cell lymphoma located in the body cavities, characterized by pleural, peritoneal, and pericardial fluid lymphomatous effusions and that is always associated with human herpes virus-8 (HHV-8). "A similar approach led to the identification of a short peptide derived from FLICE-like inhibitor protein (FLIP), an inhibitor of ATG3, which can unleash ATG3 from FLIP inhibition and induce massive cell death of virus-associated primary effusion lymphoma through autophagy activation." (PMID 36670319, 2023).
psoriasis (1 paper, 2025). An autoimmune condition characterized by red, well-delineated plaques with silvery scales that are usually on the extensor surfaces and scalp. "We found the expression of the gene ATG16L to be significantly suppressed and that of the genes ATG3 and ATG4C to be significantly higher in the lesional skin of psoriasis patients compared to controls and to non-lesional skin." (PMID 40565008, 2025).
reovirus infection (1 paper, 2017). "To examine the importance of the autophagy machinery for reovirus infection, we used SV40 transformed MEF cell lines with a knock-out for a specific autophagy-related gene: Atg3, Atg5, or Atg13." (PMID 28934149, 2017).
restless legs syndrome (1 paper, 2025). A condition that occurs while resting or lying in bed; it is characterized by an irresistible urgency to move the legs to obtain relief from a strange and uncomfortable sensation in the legs. "The receiver operating characteristic curve analyze results and optimal cut‐off levels of ATG3 and ATG5 in patients with restless legs syndrome." (PMID 39776356, 2025).
Sepsis (1 paper, 2018). Sepsis is defined as life-threatening organ dysfunction caused by a dysregulated host response to infection. "In the present study, HIPK2 overexpression significantly enhanced the increased expression of the Atg12-5 complex and restored the reduced Atg3 expression in mice with sepsis-induced liver injury." (PMID 30154452, 2018).
Splenomegaly (1 paper, 2022). Abnormal increased size of the spleen. "Recurrence of splenomegaly was also observed after silencing of Atg3." (PMID 35582751, 2022).
Stroke (1 paper, 2023). Sudden impairment of blood flow to a part of the brain due to occlusion or rupture of an artery to the brain. "Inhibition of autophagy by ATG3 silencing activated the phosphoinositide 3-kinase (PI3K)/Akt pathway and attenuated inflammation in OGD/R-challenged brain microvascular endothelial cells, indicating that the ATG3-mediated autophagy might play a detrimental role in stroke." (PMID 37305740, 2023).
vasculitis (1 paper, 2022). "Next, to determine whether Atg3 is responsible for the protective effect of melatonin in CAWS‐induced KD vasculitis, we injected a lentivirus carrying shRNA into mice, to silence Atg3, and then administered melatonin according to the modelling timeline." (PMID 35582751, 2022).
tumor (34 papers, 2017 to 2026). "Increased expression of ATG3 has been linked to enhanced autophagic activity, promoting tumor cell survival under stress conditions, which is particularly relevant in the tumor microenvironment of NPC." (PMID 40630202, 2025). "IHC staining of tumor tissue sections showed that subcutaneous tumors transfected with LV-sh-HDAC2 had decreased ATG3 expression, increased p62 expression, and significantly reduced proliferation." (PMID 39147759, 2024). "ATG3 also is involved in many physiological and pathological processes in an autophagy-dependent manner, such as tumor progression, maintaining mitochondrial homeostasis, etc.." (PMID 39768248, 2024). "For example, long non-coding RNA PVT1 is reported to be closely related to autophagy and has been proved to affect tumor autophagy via miR-365/ATG3, miR-20a-5p/ULK1, miR-619-5p/ATG14 or multiple axes." (PMID 34823534, 2021). "In general, the expression and modification of ATG3 play important roles in tumor development and progression." (PMID 34235149, 2021). "ATG3 can also interact with cellular and viral FLIPs (death effector domains) to suppress autophagy, resulting in tumor development." (PMID 34235149, 2021). "ATG3 is related to cell autophagy, and several studies have found that aberrant expression of ATG3 can increase cell autophagy, which is related to enhanced drug-resistance of tumor cells." (PMID 34457004, 2021). "The promotion of ATG3 on tumor cells has been confirmed by several studies, and ATG3 was regulated by multiple miRNAs to involve the malignant progression of some tumor cells." (PMID 34457004, 2021). "ATG3 has also been found to participate in many physiological and pathological processes in an autophagy-dependent manner, such as tumor occurrence and progression, ischemia–reperfusion injury, clearance of pathogens, and maintenance of organelle homeostasis." (PMID 34235149, 2021). "ATG3 is reported to serve as a tumor protective factor in general, and the mechanisms of its oncogenic function are tissue-specific." (PMID 33160404, 2020). "LncRNA PVT1 significantly promoted autophagy and subsequent proliferation of tumor cells through acting as a ceRNA to target ATG3 by sponging microRNA-365 in HCC." (PMID 31761783, 2019). "Another group showed that vFLIP-derived peptides that inhibit interaction of vFLIP and autophagy-related protein 3 (ATG3) suppress tumor formation in NOD/SCID mice xenografted with PEL cells." (PMID 29746593, 2018). "Conversely, the expression of two autophagy markers, LC3 and autophagy-related gene 3 (ATG3), was significantly upregulated in normal adjacent to tumor compared with normal tissues, while HBV infection had only a limited, statistically non-significant contribution to this behavior." (PMID 39838427, 2025). "Notably, the tumor size derived from miR-622/ATG3-expressing HCT116 cells was larger than those from miR-622-expressing HCT116 cells." (PMID 35978049, 2023). "Several studies have proved that ATG3 was significantly upregulated in multiple cancers, and ATG3 downregulation could effectively inhibit the proliferation invasive abilities of tumor cells." (PMID 34457004, 2021). "In addition, ATG3 can be modified by acetyltransferases recruited by Myc box II, a region within Myc-nick, which is a cleavage product of Myc being present in most tumor samples, leading to the upregulation of autophagy and cancer cell survival." (PMID 34235149, 2021). "ATG3 has been found as a tumor promoter that involves the malignant behaviors of multiple tumors." (PMID 34457004, 2021). "In addition, Meg3 protected ATG3 mRNA from degradation following treatment with actinomycin D. Overall, our results suggest that the lncRNA Meg3 acts as a tumor suppressor in EOC by regulating ATG3 activity and inducing autophagy." (PMID 28423647, 2017). "The identification of ATG3, STK25, and DIRAS3 aligns with prior research implicating autophagy and tumor suppression mechanisms in CRC development." (PMID 41463182, 2025).
tumor (continued). "According to a previous research, LAPTM4B promotes tumor growth and autophagy in HCC cells by activating ATG3 transcription." (PMID 38114725, 2023). "Results of present study showed that the expression of ATG3, ATG5 and LC3‐II was increased in the metformin‐treated cells, indicating that autophagy was involved with the anti‐tumour effect of metformin." (PMID 34164906, 2021). "Compared with normal tissues, tumor tissues showed significantly higher mRNA levels of the following key autophagy genes: ATG5, ATG7, ATG3, ATG9A, ATG9B, ATG12, AMBRA1, and NBR1." (PMID 32582551, 2020). "From the results, we noticed that tumor cells highly expressed AUP1 significantly correlated with proliferation marker (MCM2, MCM6), PI3K-AKT-MTOR pathway (Akt1, TSC1, mTOR, Foxo1), and autophagy signaling (Atg3, Atg4B, Atg4D, Atg7, Atg9A, Atg16L1) in IDH wildtype tumor cells." (PMID 37029364, 2023). "The expression of BECN1, ATG3, and ULK1 significantly altered between normal and tumor patients." (PMID 37790849, 2023). "However, it has also been reported that there is deletion of the autophagy related genes ATG3 and ATG7 in RAS-driven early stage tumor mouse models." (PMID 34823534, 2021). "Regarding tumor cell survival, the resistance to metabolic stress induced by TMEM74 overexpression was counteracted by ATG5, ATG7, ATG16L1, ATG3 and ATG10 deficiencies but not the BECN1 and ULK1." (PMID 29048433, 2017). "Another study revealed that KCNQ1OT1 was a prognostic biomarker in non-SCLC and could accelerate tumor progression by the regulation of miR-204-5p/ATG3 axis." (PMID 35692583, 2022). "This study revealed miR-651-3p as a tumor inhibitor in HCC cells and illustrated that miR-651-3p could enhance the sensitivity of HCC cells on CDDP via regulating the aberrant autophagy levels of HCC cells induced by increased ATG3." (PMID 34457004, 2021). "Moreover, another study showed that CD4+ T cells lacking Atg3 or Atg5 can increase IL-9 expression and autophagy inhibition enhanced T helper 9 cell anticancer effects in vivo, and mice with T cell-specific deletion of Atg5 showed decreased tumor outgrowth in an IL-9-dependent manner." (PMID 38627815, 2024).
cancer (28 papers, 2012 to 2025). A tumor composed of atypical neoplastic, often pleomorphic cells that invade other tissues. "Research has shown that ATG3 is degraded via Tyr203 phosphorylation during etoposide or cisplatin treatment, causing DNA damage in cancer cell lines." (PMID 34235149, 2021). "Molecular mechanisms underlying Atg8 lipidation remain poorly understood despite association of Atg3, the E1 Atg7, and the composite E3 Atg12–Atg5-Atg16 with pathologies including cancers, infections and neurodegeneration." (PMID 31399562, 2019). "Furthermore, since AKT inhibition promotes autophagy during cancer cell death, we investigated whether the genes associated with autophagy, including Atg3, Becn1, and Atf4, were upregulated or downregulated using qPCR." (PMID 38732133, 2024). "The oncogenic effects of ATG3 are primarily mediated through an autophagy-dependent pathway, evidenced by the counteractive effects of autophagy blockade on cancer progression." (PMID 41463182, 2025). "A 1.89-fold increase was observed in the transcriptional levels of ATG3 after the cancer cells treatment with N. nuda extract." (PMID 39768248, 2024). "The expression of ATG3 changes significantly in various types of cancer tissues, indicating that the expression level of ATG3 is closely related to cancer." (PMID 34235149, 2021). "LncRNAs with an oncogenic function such as lncRNA-HOTAIR, lncRNA-PVT1, and lncRNA-GAS5 can stabilize ATG3 mRNA and increase its expression in cancer cells." (PMID 33160404, 2020). "Considering that autophagy is a double-edged sword for cancer cells, especially in the condition of stress, we investigated the effect of Atg3 following bortezomib treatment." (PMID 27391105, 2016). "Continued research on how Atg3 is up-regulated and how autophagy promotes cancer resistances are needed." (PMID 23119048, 2012). "It was indeed reported that Beclin-1, but also ATG5 and ATG3, are caspase-8 substrates in vitro, and that after death receptor activation in several cancer cells, the subsequent downregulation of autophagic flux is partly due to caspase-8-dependent cleavage of these autophagic proteins." (PMID 36418547, 2023). "Under DNA damage conditions, protein tyrosine kinase 2 (PTK2) phosphorylates ATG3 at the Tyr203 site and promotes the degradation of ATG3 through the ubiquitin-dependent proteasome pathway, resulting in positively regulating the activity of cancer cells." (PMID 35806307, 2022). "Our findings showed that cancer-derived exosomal miR-651 restrained cisplatin resistance and directly targeted ATG3, indicating that exosomal miR-651 could be a therapeutic agent." (PMID 34567283, 2021). "Also, we demonstrated that erlotinib-cisplatin combination is an effective treatment against erlotinib resistant cancer cells by targeting autophagy through down-regulation of Atg3 and induction of apoptotic cell death." (PMID 23119048, 2012). "Also, we demonstrate that combination erlotinib-cisplatin is an effective treatment against erlotinib resistant cancer by targeting (down-regulating) Atg3 mediated autophagy and induction of apoptotic cell death." (PMID 23119048, 2012). "Therefore, melatonin‐promoted ATG3 and Beclin 1 expression in CD133− cells might be associated with other cancer stem cell subpopulations." (PMID 37307404, 2023). "HOTAIRM1 functions as a ceRNA to regulate autophagy initiation and elongation through ULK1, ATG3, ATG7, and ATG12 in cancers." (PMID 33050642, 2020). "Taken together, the current data demonstrate that ceRNAs can participate in many steps of autophagy by upregulating some key molecules, such as ULK1, ATG3, ATG7, and ATG4, resulting in chemoresistance in various cancers." (PMID 33050642, 2020). "However, when compared to non‐resistant cancer cells (i.e., LSCC), only two of them, namely, ATG3, and ULK1 were upregulated, whereas the other three were downregulated in DR‐LSCC." (PMID 40385549, 2025).
cancer (continued). "ATG3 was upregulated in CRC tissues and cell lines compared to normal counterparts, with experimental evidence showing that ATG3 knockdown significantly suppresses cancer cell proliferation and invasion." (PMID 41463182, 2025). "Specifically, Cas9 knockout of ATG3/ATG7, could disrupt autophagy flux and sensitize the cancer cells to etoposide." (PMID 28981103, 2017). "Interestingly, several of these proteins are also known to be important in MYC-driven cancers like ribosome components (such as Rps8), multiple subunits of the eukaryotic translation initiation factor 3 complex, and proteins important for MYC-induced autophagy (such as Atg3)." (PMID 38302473, 2024).
infection (21 papers, 2016 to 2025). The state of being infected such as from the introduction of a foreign agent such as serum, vaccine, antigenic substance or organism. "atg-3 mutants phenocopy rde-1 mutants, which have a defect in RNA interference (RNAi), in susceptibility to Orsay virus infection and transcriptional response to infection." (PMID 39868230, 2025). "Our data suggest that ATG-3 and its regulation of sqt-2 could be more relevant to viral egress than viral entry, since bypassing viral entry in atg-3-mutant replicon worms led to a similar enhanced susceptibility to infection compared to rde-1 mutants." (PMID 41252446, 2025). "The finding that unstarved worms were more susceptible to infection with Orsay virus than re-fed worms but have a higher level of autophagic flux suggests that the role of ATG-3 in resistance to Orsay virus infection could be independent of its role in canonical autophagy." (PMID 39868230, 2025). "Our data suggest that ATG-3 and its regulation of sqt-2 could be more relevant to viral egress than viral entry, since bypassing viral entry in atg-3-mutant replicon worms led to a similar enhanced susceptibility to infection." (PMID 39868230, 2025). "We found that, like rde-1 mutants, atg-3 mutants exhibited robust induction of IPR gene expression upon infection." (PMID 39868230, 2025). "BECN1 and ATG3 mRNA were significantly increased after 24 h post-infection (hpi) as compared to their respective uninfected controls." (PMID 32512864, 2020). "For instance, Beclin1, PI3K/VPS30, and ATG3 are all required to limit HR PCD to the pathogen infection site, ATG5 and ATG7 regulate glucose-induced ROS in Arabidopsis, and ATG9 is a negative regulator of innate immune signaling." (PMID 32373106, 2020). "Late in infection, when miR-155 expression peaked, both the level of Atg3 and the number of LC3 puncta per cell (autophagosomes) decreased dramatically." (PMID 29300789, 2018). "In addition, Mycobacterium tuberculosis, a bacterial pathogen, inhibits translation of ATG3 to promote pathogen survival, suggesting that ATG3 is relevant to defense against infection." (PMID 39868230, 2025). "We also investigated the impact of VgrG2 on the mTOR signaling pathway by examining the transcription levels of key genes, including mTOR, ULK1, Beclin-1, P62, LC3, Atg3, Atg5, and Atg12, following infection, and assessed the expression of the autophagy marker protein LC3-II." (PMID 40266908, 2025). "To determine whether LM induced an increase in autophagy-related gene expression in B16F10 cells, we detected the relative expression of Atg3, Atg5, Beclin-1, and p62 mRNA at 4 h post-infection by real-time PCR." (PMID 36838373, 2023). "However, transduction titers in HeLa/IDO1/shAtg3 cells were lower than those in HeLa/shAtg3 cells, showing that IDO1 expression inhibited HIV-1-based vector infection in the Atg3-silenced cells." (PMID 35883685, 2022). "To confirm the absence of regulation of major genes involved in the autophagic machinery, we verified the expression of two key genes, BECN1 (involved in autophagic vacuole formation) and ATG3 (involved in the ubiquitination process) during the course of infection." (PMID 34835061, 2021). "We observed that compared to wild-type MEFs, a greater percentage of Atg3−/− MEFs remained infected with L. donovani throughout the 72-h time course of the infection and that the number of L. donovani amastigotes per host cells was significantly higher in Atg3−/− MEFs compared to wild-type cells." (PMID 32723921, 2020). "In non-treated cells, infection with MERS-CoV-MA-WT significantly reduced ATG3 and LC3A mRNA levels, while MERS-CoV-MA-Δ4b-infection increased ATG3 mRNA levels." (PMID 36129908, 2022). "The result suggested that the host Atg3 and Atg5 are binding proteins of CDPK3 during infection with the less virulent ME49 strain." (PMID 35757711, 2022).